PLEKHB2 (pleckstrin homology domain containing B2)
Description:
Involved in retrograde transport of recycling endosomes.
Synonyms: EVT2; FLJ20783
Tractability: Small molecule: a structure with a bound ligand is known. Antibody: UniProt places it where antibodies can reach, with high confidence. PROTAC: ubiquitination databases record sites on it.
Gene: Protein-coding gene on chromosome 2 (131,104,847 to 131,353,709, forward strand). Ensembl gene ENSG00000115762.
Subcellular location: Recycling endosome membrane
Gene Ontology:
Molecular function: phosphatidylinositol-3,4,5-trisphosphate binding; protein binding
Biological process: regulation of cell differentiation
Cellular component: membrane; recycling endosome membrane
Genetic constraint (gnomAD): Loss-of-function variants: 13 observed, 16.72 expected, observed/expected ratio (o/e) 0.78, 90% interval 0.5 to 1.24. The upper end of that interval is the gene's LOEUF score, 1.24, which puts it in group 5 of 6, group 1 being the genes least tolerant of losing a copy. Missense variants: 134 observed, 151.7 expected, observed/expected ratio (o/e) 0.88, 90% interval 0.77 to 1.02. Synonymous variants: 52 observed, 55.02 expected, observed/expected ratio (o/e) 0.95, 90% interval 0.75 to 1.19.
Homologues: Orthologues: macaque PLEKHB2 (98% identical), pig PLEKHB2 (94% identical), rabbit PLEKHB2 (92% identical), mouse Plekhb2 (90% identical), dog PLEKHB2 (90% identical), rat Plekhb2 (90% identical), guinea pig PLEKHB2 (88% identical), tropical clawed frog plekhb2 (63% identical), zebrafish plekhb2 (58% identical). Paralogues in human: PLEKHB1 (41% identical).
Diseases named in the same sentence as PLEKHB2 in open-access papers:
PLEKHB2 is named in the same sentence as 12 diseases in open-access papers, as found by Europe PMC text mining. Sharing a sentence is not in itself a finding about the gene and the disease. The quoted sentences say what the papers report.
Arrhythmia (1 paper, 2023). Any cardiac rhythm other than the normal sinus rhythm. "PTPRQ, PLEKHB2, IL1RAPL1, and EXT1 are predicted to be involved in biological processes such as heart and large blood vessel development, as well as cardiac phenotypes such as arrhythmias, valve diseases, and cardiomyopathy." (PMID 37684230, 2023).
colon cancer (1 paper, 2022). "Another gene, PLEKHB2 (also called evectin-2), negatively correlated with the DLK2 level, plays a critical role in the YAP oncogenic pathway of proliferating cells, and it is also downregulated in colon cancer." (PMID 35456435, 2022).
melanoma (1 paper, 2023). A malignant, usually aggressive tumor composed of atypical, neoplastic melanocytes. "Associations with the presence of TERT promoter mutations revealed an overlap of 30 genes in the three bulk RNA-seq cohorts (in melanoma and across entities), of which six genes were consistently up- or down-regulated (up: ARL17A, FBF1, KAZALD1, PRAF2; down: PLEKHB2, RASGRP3)." (PMID 37418389, 2023).
PLEKHB2 also shares sentences with these, for which no sentence is quoted: breast carcinoma (2 papers); infection (2); atherosclerosis (1); cancer (1); cardiomyopathy (1); metastatic cancer (1); neurodegenerative disease (1); preeclampsia (1); tumor (1).